LINC00486 (long independently transcribed non-coding RNA 486)
Gene: Long non-coding RNA gene on chromosome 2 (32,825,261 to 32,926,693, forward strand). Ensembl gene ENSG00000230876.
Diseases named in the same sentence as LINC00486 in open-access papers:
LINC00486 is named in the same sentence as 6 diseases in open-access papers, as found by Europe PMC text mining. Sharing a sentence is not in itself a finding about the gene and the disease. The quoted sentences say what the papers report.
breast carcinoma (1 paper, 2022). "A recent study also found that LINC00486 may act as a tumor suppressor gene and its overexpression can inhibit the proliferation and promote the apoptosis of breast cancer tissues by suppressing miR-182–5p expression." (PMID 35399499, 2022).
colon adenocarcinoma (1 paper, 2024). "LINC00342 has been found to be upregulated in colon adenocarcinoma promoting cell proliferation and invasion, whereas LINC02691 and LINC00486 expression correlates with overall survival and prognosis in hepatocellular and gastric carcinoma, respectively." (PMID 39217365, 2024).
non-small cell lung carcinoma (1 paper, 2021). A group of at least three distinct histological types of lung cancer, including non-small cell squamous cell carcinoma, adenocarcinoma, and large cell carcinoma. "In non-small cell lung cancer cells, the LINC00486 gene is a hot spot of breakpoints that demonstrate an extremely high rearrangement rate and might correspond to a new fragile site." (PMID 34359791, 2021).
LINC00486 also shares sentences with these, for which no sentence is quoted: gastric carcinoma (1 paper); neurological disorders (1); tumor (1).